NDST4 (N-deacetylase and N-sulfotransferase 4)
Description:
Essential enzyme that catalyzes the N-sulfation of glucosamine (GlcNAc) of the glycosaminoglycan in heparan sulfate. Modifies the GlcNAc-GlcA disaccharide repeating sugar backbone to make N-sulfated heparosan, a prerequisite substrate for later modifications in heparin biosynthesis. Has no deacetylase activity but high sulfotransferase activity. Plays a crucial role in the differentiation of colonic progenitor cells (By similarity).
Synonyms: NDST-4; N-HSST; N-HSST 4; NHSST4
Tractability: Antibody: UniProt predicts a signal peptide or a membrane-spanning region.
Gene: Protein-coding gene on chromosome 4 (114,827,763 to 115,113,876, reverse strand). Ensembl gene ENSG00000138653.
Subcellular location: Golgi apparatus membrane
Pathways (Reactome):
Metabolism: HS-GAG biosynthesis
Gene Ontology:
Molecular function: deacetylase activity; heparan sulfate N-sulfotransferase activity; hydrolase activity; N-acetylglucosamine deacetylase activity; sulfotransferase activity
Biological process: heparan sulfate proteoglycan biosynthetic process; heparin proteoglycan biosynthetic process
Cellular component: Golgi apparatus; Golgi membrane
Genetic constraint (gnomAD): Loss-of-function variants: 47 observed, 77.54 expected, observed/expected ratio (o/e) 0.61, 90% interval 0.48 to 0.77. The upper end of that interval is the gene's LOEUF score, 0.77, which puts it in group 3 of 6, group 1 being the genes least tolerant of losing a copy. Missense variants: 807 observed, 888.6 expected, observed/expected ratio (o/e) 0.91, 90% interval 0.86 to 0.96. Synonymous variants: 330 observed, 322.78 expected, observed/expected ratio (o/e) 1.02, 90% interval 0.93 to 1.12.
Homologues: Orthologues: chimpanzee NDST4 (99% identical), macaque NDST4 (99% identical), pig NDST4 (98% identical), dog NDST4 (97% identical), guinea pig NDST4 (96% identical), mouse Ndst4 (96% identical), rat Ndst4 (96% identical), rabbit NDST4 (94% identical), tropical clawed frog ndst4 (84% identical), zebrafish ndst3 (76% identical). Paralogues in human: NDST3 (82% identical), NDST1 (71% identical), NDST2 (68% identical), HS3ST3A1 (14% identical), HS3ST4 (14% identical), HS3ST2 (13% identical), HS3ST3B1 (13% identical), HS3ST1 (11% identical), HS3ST6 (11% identical), HS3ST5 (11% identical).
Diseases named in the same sentence as NDST4 in open-access papers:
NDST4 is named in the same sentence as 19 diseases in open-access papers, as found by Europe PMC text mining. Sharing a sentence is not in itself a finding about the gene and the disease. The quoted sentences say what the papers report.
colorectal cancer (7 papers, 2013 to 2025). A primary or metastatic malignant neoplasm that affects the colon or rectum. "Genetic loss of NDST4 is significantly associated with tumor progression, and NDST4 gene is identified as a novel candidate tumor suppressor in human colorectal cancer." (PMID 41149035, 2025). "Genetic loss of NDST4 in colorectal cancer and high HS 3-O-sulphotransferase 3A expression in HER2-positive breast cancer patients were shown to be associated with poor prognosis." (PMID 30054430, 2018). "In colorectal cancer, NDST4 loss of function was implicated in tumor progression and the gene was considered a candidate tumor suppressor." (PMID 29854292, 2018). "Association of genetic loss of NDST4 with clinicopathological characteristics of patients with colorectal cancer." (PMID 23825612, 2013). "Allelic loss of NDST4 gene was further determined in 174 colorectal carcinomas by loss of heterozygosity analysis, and then was assessed for clinical relevance." (PMID 23825612, 2013). "NDST4 was previously identified as a putative tumor-suppressor gene in human colorectal cancer and its genetic loss might be related to the colorectal cancer progression." (PMID 29297280, 2017). "Recently, NDST4 was identified as a tumor suppressor linked to colorectal cancer." (PMID 28672878, 2017). "In a previous study, by using the loss of heterozygosity approach, we identified, for the first time, NDST4 as a novel putative tumor suppressor gene associated with human cancer, and the loss of its function might be involved in the progression of colorectal cancer." (PMID 27793051, 2016). "In total, 30 (57.7%) of 52 colorectal carcinomas showed a dramatic reduction in NDST4 gene expression compared with matched normal mucosae." (PMID 23825612, 2013). "We previously identified NDST4 as a putative tumor suppressor in human colorectal cancer." (PMID 27793051, 2016). "Thus, the findings of this study provide insights into the physiological role of NDST4 in the development and homeostasis of the human colonic epithelium, and suggest that NDST4 downregulation promotes the tumorigenesis and progression of colorectal cancer." (PMID 27793051, 2016).
breast carcinoma (4 papers, 2018 to 2022). "That said, in certain tumor types, expression of these molecules has been described, for example, NDST4 in breast cancer, although in RSCRCs neither was detected." (PMID 29940912, 2018).
adenoma (1 paper, 2013). A neoplasm arising from the epithelium. "Unlike CRC tumors, in which NDST4 expression was decreased substantially, the adenomas showed a similar level of expression as normal mucosae." (PMID 23825612, 2013).
autism (1 paper, 2021). Persistent deficits in social interaction and communication and interaction as well as a markedly restricted repertoire of activity and interest as well as repetitive patterns of behavior. "Variants in NDST4 were associated with ASD, variants in RORB were associated with childhood autism, and variants in SETBP1 were associated with schizophrenia." (PMID 34773992, 2021). "Tests for three genes obtained nominally significant p values: NDST4 in ASD, RORB in childhood autism, and SETBP1 in schizophrenia." (PMID 34773992, 2021).
colitis (1 paper, 2016). Inflammation of the colon. "Accordingly, the results might predict that a colitis-prone phenotype occurs following Ndst4 deficiency, which is being investigated using the genetically engineered mouse strain generated in the present study." (PMID 27793051, 2016).
Fever (1 paper, 2022). Body temperature elevated above the normal range. "NDST4 is associated with milk fever in the U.S. Holstein cattle." (PMID 36134029, 2022).
glioblastoma (1 paper, 2019). The most malignant astrocytic tumor (WHO grade IV). "In TCGA datasets, 8 missense mutations and deletions in NDST4 were found in lower grade gliomas, while 17 missense and 1 truncating variant were found in glioblastoma." (PMID 31217899, 2019).
Hypocalcemia (1 paper, 2020). An abnormally decreased calcium concentration in the blood. "The top associated region for hypocalcemia is around 10,521,824 bp on BTA 6, where QTLs were reported for body/carcass weight and reproduction traits with nearby genes being Translocation Associated Membrane Protein 1 Like (TRAM1L1) and N-Deacetylase And N-Sulfotransferase (NDST4)." (PMID 31931710, 2020).
Insulin resistance (1 paper, 2017). Increased resistance towards insulin, that is, diminished effectiveness of insulin in reducing blood glucose levels. "NDST4 has been found to be associated with levels of circulating resistin, a hormone reported to be associated with insulin resistance, T2D, and cardiovascular disease." (PMID 29079728, 2017).
lung carcinoma (1 paper, 2019). "These genes are altered in many cancers and like NDST4, frequent alterations are present in skin cutaneous melanoma and lung cancer." (PMID 31217899, 2019).
oligodendroglioma (1 paper, 2019). A well-differentiated (WHO grade II), diffusely infiltrating neuroglial tumor, typically located in the cerebral hemispheres. "Thus, although NDST4 remains a gene of interest in tumor development and indeed might play a role in the progression from primary O2005 to recurrent O2010, NDST4 mutation seems to be a rare event in oligodendroglioma." (PMID 31217899, 2019). "To investigate if alterations in NDST4 might play a role in the development of oligodendroglioma, we performed Sanger sequencing to analyze all coding exons of the gene in our own cohort of primary oligodendrogliomas (n = 15)." (PMID 31217899, 2019). "Sequencing of NDST4 in a cohort of 15 oligodendrogliomas, however, revealed no additional cases with potential protein disrupting variants." (PMID 31217899, 2019).
tumor (9 papers, 2013 to 2025). "NDST4 was a candidate tumor suppressor gene on chromosome 4 as the NDST4 previous variant was already detectable in the primary tumor and the wild-type allele was lost in recurrent O2010, indicating a loss of function mechanism." (PMID 31217899, 2019). "Finally, the increase in allele frequency of the NDST4 variant in the tumor series was consistent with the selection of a tumor suppressor gene." (PMID 31217899, 2019). "In addition, we developed an LOH assay with two microsatellite markers, and revealed that the genetic loss of NDST4 was significantly associated with advanced pathological stage and poor survival, supporting the tumor suppressor function of NDST4 in CRC." (PMID 23825612, 2013). "NDST4 on chromosome 4q emerged as a potential tumor suppressor gene as it was one of the few genes with a variant already detectable in primary O2005." (PMID 31217899, 2019). "Our analysis illuminated a tumor evolutionary series of events, which included 1p/19q codeletion, IDH1 R132H, and TERT C250T as early events, followed by loss of function of NDST4 and mutations in FUBP1 and CIC as late events." (PMID 31217899, 2019). "By laser capture microdissection, NDST4 RNA expression was demonstrated in colonic epithelial cells, but was undetectable in tumor cells." (PMID 23825612, 2013). "Taken together, further studies are warranted to get insights into the role of NDST4 in tumor development and progression of human cancers." (PMID 23825612, 2013). "NDST4 (N-deacetylase/N-sulfotransferase 4) is a tumor suppressor gene located on chromosome 4q26." (PMID 40740242, 2025). "We found no variants in coding regions of NDST4 in this tumor set; only known polymorphisms and variants in intronic sequences were observed." (PMID 31217899, 2019). "A novel candidate tumor suppressor gene, namely NDST4, was identified at 4q26." (PMID 23825612, 2013). "NDST4 (N-deacetylase/N-sulfotransferase-4), is involved in heparan sulfate (HS) biosynthesis and may be implicated in positive or negative aspects of tumor progression." (PMID 29854292, 2018). "Interestingly, the NDST4 gene, located also at 4q26, and belonging to the same family than NDST3, has been identified as a possible tumour suppressor gene in CRC." (PMID 24978480, 2014). "The results showed that NDST4 mRNA was detectable in epithelial cells from both cases of normal mucosae, but neither in their paired tumor cells nor in lymphoid cells, even after 45 cycles of PCR amplification." (PMID 23825612, 2013). "Therefore, laser capture microdissection was conducted to isolate different cell types in the tissue sections, including the epithelial and lymphoid cells of normal mucosa, as well as the tumor cells of CRC, and then NDST4 expression was determined by qRT-PCR." (PMID 23825612, 2013).
cancer (5 papers, 2013 to 2021). A tumor composed of atypical neoplastic, often pleomorphic cells that invade other tissues. "NDST4 gene is a novel candidate tumor suppressor gene in human cancer, and the loss of its function might be involved in CRC progression." (PMID 23825612, 2013). "Ndst4 is involved in N-sulfation of heparin sulfate chains and is downregulated in carcinoma, indicating an anti-proliferative or pro-differentiative role." (PMID 26447881, 2015). "In addition, SNVs were detected in genes that were previously associated with cancer, such as CACNA1E, PRKD1, NDST4, and were also considered pathogenic/deleterious/not tolerated in at least three mutation function models." (PMID 29854292, 2018).
colorectal (1 paper, 2013). "A dramatic reduction of NDST4 expression in CRC sustains that NDST4 is a novel candidate TSG, and that the loss of its function might play a role in colorectal tumorigenesis." (PMID 23825612, 2013).
NDST4 also shares sentences with these, for which no sentence is quoted: glioma (1 paper); infiltrating ductal adenocarcinomas (1); intestinal diseases (1); schizophrenia (1); skin cutaneous melanoma (1).